CTBP1-AS (CTBP1 antisense RNA)
Synonyms: PCAT10
Gene: Long non-coding RNA gene on chromosome 4 (1,210,120 to 1,218,591, forward strand). Ensembl gene ENSG00000280927.
Diseases named in the same sentence as CTBP1-AS in open-access papers:
CTBP1-AS is named in the same sentence as 4 diseases in open-access papers, as found by Europe PMC text mining. Sharing a sentence is not in itself a finding about the gene and the disease. The quoted sentences say what the papers report.
prostate (1 paper, 2020). "For example, the DE-lncRNAs PVT1, PCAT1, and PCAT10/CTBP1-AS have been previously studied and implicated in prostate tumorigenesis." (PMID 32059012, 2020).
CTBP1-AS also shares sentences with these, for which no sentence is quoted: cancer (1 paper); prostate tumors (1); tumor (1).